BRAF (B-Raf proto-oncogene, serine/threonine kinase)
Diseases named in the same sentence as BRAF in open-access papers (continued):
Sharing a sentence is not in itself a finding about the gene and the disease.
melanoma (continued). "BRAF gene mutation has been identified in about 6% of human cancers, including melanomas (40–50%), thyroid cancers (10–70%), colorectal cancers (~10%), and non-small cell lung cancer (3–5%)." (PMID 35048058, 2021). "Stage III melanoma patients with BRAF mutation treated with adjuvant RT had > 4 times increased risk of local recurrence or regional lymph node recurrence." (PMID 34537078, 2021). "For example, although the majority of melanomas carry one or more BRAF mutations, many studies have demonstrated that BRAF mutations are sufficient for the development of early lesion, but additional genetic alterations are needed for malignant transformation." (PMID 34282258, 2021). "Several studies have indicated a strong correlation between protein expression and molecular analysis of BRAF mutations in melanomas." (PMID 34769348, 2021). "The identification of melanoma driver mutations in the MAPK/ERK pathway resulted in the development of BRAF small molecule inhibitors (vemurafenib and dabrafenib) and MEK small molecule inhibitors (trametinib and cobimetinib)." (PMID 35008286, 2021). "In melanoma, although present in much lower percentages compared to BRAF and NRAS mutations, in the last few years, several mitogen-activated protein kinase kinase (MEK) mutations have been identified." (PMID 33917181, 2021). "BRAF inhibitors such as vemurafenib or encorafenib (tyrosine kinase inhibitors specific to the ATP-binding domain of BRAF V600E) have been tested in patients with CRC or melanoma with BRAF V600E mutations." (PMID 34249672, 2021). "In agreement, Ho and co-workers showed that DC isolated from advanced BRAF-mutated melanomas were unable to stimulate the proliferation of CD8+ T cells." (PMID 34576054, 2021). "One of these, the C125S variant, was previously identified in melanoma patients who developed resistance to BRAF inhibitors." (PMID 34205480, 2021). "It plays a vital role in tumor growth, proliferation, invasion and metastasis, so BRAF-V600E mutation is one of the effective targets of anti-melanoma and other tumors." (PMID 34249939, 2021). "As widely acknowledged, 40–50% of all melanoma patients harbour an activating BRAF mutation (mostly BRAF V600E)." (PMID 33801689, 2021). "Amongst the mucosal melanoma, 34 underwent mutational testing and 4 patients had BRAF mutations (3 had v600 codon mutation and 1 non-v600 codon mutation) and another 4 had KIT mutations." (PMID 35211204, 2021). "Since 2013, Dabrafenib and Trametinb have proven to be a revolution for melanoma treatment; these drugs inhibits BRAF and MEK pathways and their use has become an important strategy to treat those forms of melanoma that present a mutation of BRAF (V600E)." (PMID 34575598, 2021). "Since then, the development of targeted therapies to suppress this signaling have given BRAF-mutation status a critical role in the clinical decision making for the treatment of advanced melanoma." (PMID 34068774, 2021). "Cutaneous melanomas harbouring BRAF V600E and V600K mutations, even if similar from a molecular point of view, have distinct clinicopathological features." (PMID 33801689, 2021). "Overall, BRAF mutation incidence was at the intermediary level compared with other melanomas, ranging from ~50% in CM, and ~10% in mucosal to 0% in uveal melanomas." (PMID 34359736, 2021). "Targeted therapy with BRAF and MEK inhibition has also been approved for the 50% of melanoma patients with activating BRAF mutations." (PMID 33732652, 2021). "This real-world analysis also demonstrated that first-line immunotherapy produced better survival outcomes compared to upfront targeted treatment in patients with BRAF mutation positive melanoma." (PMID 34677256, 2021). "BRAF mutations occur in about 8% of human cancers, including melanoma, colorectal cancer, glioma, thyroid cancer, non-small cell lung cancer, cholangiocarcinoma, and several hematological malignancies." (PMID 35145907, 2021).
melanoma (continued). "The three most prevalent genes mutated in melanoma are BRAF, neuroblastoma RAS viral oncogene homolog (NRAS), and neurofibromatosis 1(NF1), and all participate in the mitogen-activated protein kinase (MAPK) signaling cascade that regulates cell proliferation." (PMID 34066966, 2021). "In the early 2000s, it was established that BRAF oncogene mutations occur in a majority of melanomas." (PMID 34621046, 2021). "Our data show that advanced melanoma in women more frequently harbors a BRAF V600E mutation, while melanoma in men more frequently has a NRAS or BRAF V600K mutation." (PMID 34572865, 2021). "The expression of various receptor tyrosine kinases, like AXL, PDGFRB, and EGFR, in cutaneous melanoma occurs in MITFlow melanoma cells with a pro-invasive potential and has been associated with BRAF/MEK inhibitor resistance." (PMID 34360915, 2021). "We explore the specific BRAFV600E mutation and discuss additional gene mutations often found in conjunction with BRAF mutations that lead to melanoma." (PMID 34066966, 2021). "The MEKi Trametinib used in these studies, is an FDA-approved kinase inhibitor indicated for the treatment of melanoma, non-small cell lung cancer and thyroid cancer with BRAF V600E or V600K mutations." (PMID 34578339, 2021). "Next, we examined the effects of DUSP4 and PPP2R2A depletion in two additional melanoma cell lines, both harboring BRAF mutations." (PMID 32767816, 2021). "In this review, we discuss melanoma BRAF mutations, the genetic mechanism of BRAFi resistance, and the evidence supporting the role of senescent cells in melanoma disease progression, drug resistance and secondary cancer." (PMID 34066966, 2021). "The resistance to BRAF inhibitors, which is crucial for melanoma prognosis, is caus-ally associated with a mesenchymal-to-amoeboid transition (MAT) and shown as elicited by ligand-independent EphA2 activation." (PMID 33572284, 2021). "Targeted therapy with BRAF/MEK inhibitors with or without immune check-point inhibitors (ICI) showed significant long-term treatment benefit in BRAF V600-mutated melanoma patients." (PMID 33918490, 2021). "For UVR-driven conjunctival and other mucosal melanomas, we again advocate immunotherapies, or if tractable BRAF mutations are present, BRAF/MEK inhibitors." (PMID 33824477, 2021). "The discovery of mutant specific BRAF inhibitors, such as vemurafenib, has remarkably improved the survival of melanoma patients with oncogenic BRAF mutations." (PMID 34570440, 2021). "BRAFi, either alone or in combination with MEKi, represents a therapeutic option for treating advanced melanoma with BRAF mutations." (PMID 34771678, 2021). "A subgroup analysis of pooled data from the pembrolizumab KEYNOTE-001, -002, and -006 trials evaluated patients with advanced melanoma and known BRAF V600E/K tumor mutations who had received pembrolizumab." (PMID 34885172, 2021). "The loss of function of tumor suppressor PTEN is often found in the late stage of malignant melanoma and coincident with BRAF mutations." (PMID 34282258, 2021). "In recent years, patients with resected stage III melanoma have become eligible for adjuvant therapy with immune checkpoint blockade or BRAF-targeted therapy in case of BRAF mutation." (PMID 34557196, 2021). "In an earlier study, the sensitivity of MAPK signaling to low-molecular drug inhibitors has been recognized in BRAF-mutated melanomas." (PMID 34063141, 2021). "Although inhibitors targeting mutant BRAF, such as vemurafenib, have improved the clinical outcome of melanoma patients with BRAF mutations, the efficiency of vemurafenib is limited in many patients." (PMID 34222023, 2021).
melanoma (continued). "In Chinese population, somatic mutations of the BRAF in melanomas have a high prevalence and approximately 22% of them have V600E mutations." (PMID 34567185, 2021). "This contrasting sensitivity for MEK and histone deacetylase inhibition is in line with the data from a study that used BRAF-mutated melanoma cell lines." (PMID 34565468, 2021). "BRAF and MEK inhibitors are the first-line treatment when the activated BRAF mutation is detected in melanoma patients." (PMID 33669949, 2021). "Four patients with metastatic BRAF-mutated melanoma were rechallenged with BRAF and MEK inhibitors after progression with targeted therapy and subsequent immunotherapy (checkpoint inhibitors)." (PMID 34136385, 2021). "The introduction of BRAF and PD‐1 inhibitors for the treatment of advanced melanoma harboring V600E BRAF mutations has revolutionized the treatment of metastatic disease." (PMID 32881028, 2021). "It is worth noticing that NRAS or BRAF mutation are frequent and associated with melanoma subtypes together with cyclin D1 and other factors." (PMID 33917849, 2021). "Currently, targeted therapy with BRAF/MEK inhibition is available for melanoma patients with BRAF mutation as an alternative or an addition to ICB." (PMID 34621681, 2021). "The overexpression of MERTK was observed in melanoma cells with the BRAF V600E mutation, which are resistant to BRAF and MEK inhibitors." (PMID 33562150, 2021). "In melanomas harboring activating BRAF mutation, the treatment with BRAFi often leads to the development of the resistance to BRAFi." (PMID 33968932, 2021). "Material and methods: Human melanoma cell lines, namely M14 and A375 harboring BRAF-V600E mutation have been treated with different concentration of either BRAFi and/or MEKi in the presence or not of the non-nucleoside RTI, i.e. SPV122." (PMID 33757523, 2021). "In conclusion, while WNT5A‐deficient melanoma cells exhibit reduced Cdc42 signaling and invasion, we also identified a counteracting response to this reduction in invasion in BRAF wild‐type and BRAFV600 mutated melanoma cells treated with a BRAF inhibitor." (PMID 33969605, 2021). "Female patients more frequently harbored BRAF V600E mutant melanoma (46% versus 36%), while BRAF V600K and NRAS mutations were more prevalent in the tumors of male patients (8% versus 4% and 21% versus 18%, respectively)." (PMID 34572865, 2021). "Activating mutations in the BRAF oncogene are the most widespread genetic alterations observed in melanoma, with an incidence of up to 40–60%." (PMID 34885166, 2021). "For patients with malignant melanoma, the updated prognostic score is a further development of the GPA—the so-called melanoma molGPA—is a more complex assessment, which also includes the BRAF mutation status." (PMID 33993415, 2021). "In melanoma, afatinib was tested and, as gefitinib and lapatinib, it showed minimal cytotoxic activity alone but was more effective when combined with AKT inhibitors in vemurafenib resistant BRAF mutated melanoma." (PMID 33918490, 2021). "MITF in conjunction with mutant BRAF(V600E), an activating mutation commonly present in melanocytic lesions, trigger transformation of immortalized melanocytes, functioning as a melanoma oncogene." (PMID 34289891, 2021). "The union of the melanoma core RS and con‐GCRs comprise 11 distinct rules and are dominated by rules that contain either BRAF or NRAS mutations." (PMID 33769711, 2021). "Among the described gene mutations, mutations in the BRAF gene have recently been taken into consideration and the relationship between BRAF V600E mutation and the transformation of congenital or dysplastic nevus to malignant melanoma has been shown." (PMID 33391380, 2021).
melanoma (continued). "Higher-quality evidence on the therapeutic efficacy of B-Raf-inhibitors in GB recently came from the VE-BASKET trial, a phase 2 study of non-melanoma tumors harboring BRAF V600E mutation." (PMID 34804975, 2021). "All patients had confirmed BRAF-V600-mutations in their melanoma and 24 patients (64.9%) showed a BRAF-V600E-mutation." (PMID 34065877, 2021). "About 50% of melanoma patients exhibit a mutation in the BRAF gene (BRAF V600E), which leads to the appearance of a constitutively active kinase." (PMID 33430277, 2021). "We overview the pathophysiology, clinical presentation of BRAF-mutated melanoma, current guidelines, and present recommendations on BRAF mutation testing." (PMID 34068774, 2021). "BRAF mutations are the most common driver mutation in melanoma, accounting for approximately 50% of cases, and among these, 90% of mutations are BRAFV600E." (PMID 34831420, 2021). "Approximately ~50% of patients with melanoma have tumors that harbor a mutation of the BRAF oncogene." (PMID 34068774, 2021). "In a phase I study, we have assessed the safety of this combination and its ability to upregulate the IFN-α signature-related gene-expression levels in patients with BRAF-mutated advanced melanoma." (PMID 33407577, 2021). "Nearly 50% of melanomas have a mutation in the BRAF gene, and BRAF inhibitors have shown tremendous efficacy in this subgroup of patients." (PMID 34071228, 2021). "Activating mutations in BRAF are particularly prevalent, being associated with ∼30% of all cancers and ∼60% of melanomas." (PMID 34296750, 2021). "Oncogenic KRAS or BRAF addiction has been found in lung and colon cancers and melanomas, where KRAS or BRAF is frequently mutated." (PMID 33793658, 2021). "Since resistance is thought to be driven by activation of the downstream MAPK pathway, combination therapy with multiple inhibitions at different sites is the preferred approach to targeted melanoma with BRAF mutation." (PMID 35155453, 2021). "Celecoxib (50 nM) and trametinib (25 nM) therapeutic association was tested in vitro on a simulated melanoma tumor formed of SK-MEL-28 human melanoma cells (positive for BRAF V600E and wild type NRAS mutations) and BJ human fibroblasts, used as co-culture." (PMID 33922284, 2021). "In 40–60% of malignant melanomas, there is a mutation in the BRAF gene that leads to the activation of a signal transduction pathway relevant for tumor development." (PMID 33993415, 2021). "A number of oncogenic driver mutations are found in melanoma, though the most common occur in the gene encoding the protein kinase BRAF." (PMID 34025662, 2021). "Advances in melanoma treatment include v-Raf murine sarcoma viral oncogene homolog B (BRAF) inhibitors that target the predominant oncogenic mutation found in malignant melanoma." (PMID 34066966, 2021). "Nearly 45% of melanoma lines showed BRAF-activating mutations, and 20% showed NRAS-activating mutations; both mutations activate the ERK/MAPK (mitogen-activated protein kinase) pathway." (PMID 34577571, 2021). "The crux of this resistance is the PLX4720-mediated activation of melanoma-associated fibroblasts (MAF) which confers tolerance to BRAF inhibition via a switch from BRAF-dependent ERK signaling to BRAF-independent ERK signaling in tumor cells." (PMID 34680395, 2021). "In a series of 444 mucosal melanomas from a European population investigated by Sanger sequencing, NRAS, KIT and BRAF mutations were evenly distributed across the different mucosal melanoma subgroups." (PMID 34571863, 2021). "Certain features were identified in melanomas that harbor BRAF mutations (e.g., primary lesions located on the trunk, diagnosed in patients <50, visibly pigmented tumors and, at times, with ulceration or specific dermatoscopic features)." (PMID 34068774, 2021). "The specific patient population considered in this appraisal is patients with advanced (unresectable or metastatic) BRAF V600 mutation-positive melanoma." (PMID 32291725, 2021).
melanoma (continued). "The company provided a submission to NICE describing the use of Enco + Bini (within the context of its licensed indication) in adults with advanced (unresectable or metastatic) BRAF V600 mutation-positive melanoma." (PMID 32291725, 2021). "Newer histopathologic classifications of CM define these subtypes as occurring on skin without high cumulative sun damage (CSD), i.e., low-CSD melanoma, and SSM and NM are more likely to harbor the BRAF V600 mutation compared to other melanoma subtypes." (PMID 33827477, 2021). "Another prospective cohort study suggested that melanoma patients with BRAF and NRAS mutation had an increased risk of tumor recurrence following a negative sentinel lymph node status." (PMID 34209415, 2021). "We aimed to assess brain metastasis free survival (BMFS), overall survival (OS), incidence of brain metastases, and sequencing strategies of immunotherapy and targeted therapy in patients with BRAF‐mutated advanced melanoma." (PMID 34137219, 2021). "In contrast, expressed PTEN regulates IGF1R-mediated BRAF inhibitor resistance in some melanoma, while melanoma with PTEN loss decreased IGF1R56." (PMID 34282258, 2021). "After testing BRAF status in primary melanoma and lymph node samples, they demonstrated that BRAF mutation was associated with a 4.5-fold higher risk of death compared to the wild-type group, suggesting a notable role of the kinase in tumor spread." (PMID 33925387, 2021). "NRAS+ melanoma genotypes are associated with lower degrees of lymphocyte infiltration, and BRAF+ genotypes are associated with a younger age of diagnosis." (PMID 34638397, 2021). "Obviously, SIJ1777 is clearly superior to vemurafenib and PLX8394 not only in terms of cellular potency but also inhibitory effects on MAPK/AKT signaling, migration/invasion, and colony formation on melanoma cells harboring BRAF class II/III mutations." (PMID 33917428, 2021). "In BRAF-mutant melanomas, loss of p19ARF promotes the epigenetic silencing of XPC, leading to deficiencies in nucleotide excision repair." (PMID 34210801, 2021). "The BRAF inhibitor, vemurafenib, has been widely used in the treatment of patients with melanoma-bearing BRAFV600E mutations." (PMID 34570440, 2021). "Somatic BRAF mutation is seen in approximately 50% of melanomas, which are typically consequences of sun exposure damage." (PMID 34155457, 2021). "It is being combined with the MEK inhibitor binimetinib to demonstrate more potent inhibition and efficacy in BRAF-mutated melanomas." (PMID 34441278, 2021). "On 29 August 2018, EMA approved dabrafenib and trametinib for stage III BRAF V600 mutated melanoma patients after complete resection of metastases." (PMID 34065995, 2021). "BRAF V600E mutation appears in up to 50% of melanoma cases, which results in the oncogenic activation of MAPK pathway." (PMID 34702444, 2021). "Following the identification of the activating BRAF-V600 mutation in melanoma, the BRAF targeting small molecule Vemurafenib was approved for cancer treatment by the Federal Drug Administration (FDA) in 2011." (PMID 33917267, 2021). "This inhibitor combination showed a high response rate, a favourable toxicity profile, and impressive progression-free survival (approximately 16.9 months compared to the ~9-month BRAFi monotherapy) in melanoma patients with BRAF mutations." (PMID 34885166, 2021). "The discovery of mutations of the BRAF gene in human cancer cells in 2002 laid the groundwork for the targeted therapy of melanoma." (PMID 33804800, 2021). "Vemurafenib and encorafenib, which are inhibitors of oncogenic BRAF kinase, are commonly used in melanoma with BRAF mutation." (PMID 33546228, 2021).